DNAAF19 (dynein axonemal assembly factor 19)
Description:
Dynein-attachment factor required for cilia motility.
Synonyms: CCDC103; FLJ13094; FLJ34211; PR46b; CILD17; SMH
Tractability: Antibody: its Gene Ontology location is reachable by antibodies, with medium confidence. PROTAC: ubiquitination databases record sites on it.
Gene: Protein-coding gene on chromosome 17 (44,899,142 to 44,905,390, forward strand). Ensembl gene ENSG00000167131.
Subcellular location: Cytoplasm; Cell projection, cilium, flagellum
Subcellular location (Human Protein Atlas): Connecting piece; Cytosol; Mid piece
Gene Ontology:
Molecular function: protein binding; protein homodimerization activity
Biological process: axonemal dynein complex assembly; cilium movement; determination of digestive tract left/right asymmetry; heart looping; inner dynein arm assembly; outer dynein arm assembly; determination of left/right symmetry; epithelial cilium movement involved in determination of left/right asymmetry; epithelial cilium movement involved in extracellular fluid movement
Cellular component: axoneme; cytoplasm; extracellular region; motile cilium; outer dynein arm
Genetic constraint (gnomAD): Loss-of-function variants: 9 observed, 12.49 expected, observed/expected ratio (o/e) 0.72, 90% interval 0.43 to 1.26. The upper end of that interval is the gene's LOEUF score, 1.26, which puts it in group 5 of 6, group 1 being the genes least tolerant of losing a copy. Missense variants: 272 observed, 311.39 expected, observed/expected ratio (o/e) 0.87, 90% interval 0.79 to 0.97. Synonymous variants: 118 observed, 130.96 expected, observed/expected ratio (o/e) 0.9, 90% interval 0.77 to 1.05.
Gene-disease validity (ClinGen):
ClinGen rates the evidence that DNAAF19 causes each of these diseases.
primary ciliary dyskinesia 17 (autosomal recessive): Definitive.
Homologues: Orthologues: chimpanzee CCDC103 (99% identical), macaque CCDC103 (94% identical), dog DNAAF19 (83% identical), mouse Ccdc103 (79% identical), rabbit DNAAF19 (78% identical), rat Ccdc103 (77% identical), guinea pig DNAAF19 (70% identical), zebrafish dnaaf19 (45% identical), tropical clawed frog dnaaf19 (41% identical).
Diseases named in the same sentence as DNAAF19 in open-access papers:
DNAAF19 is named in the same sentence as 16 diseases in open-access papers, as found by Europe PMC text mining. Sharing a sentence is not in itself a finding about the gene and the disease.
DNAAF19 shares sentences with these, for which no sentence is quoted: primary ciliary dyskinesia (5 papers); cancer (2); ciliopathy (2); emphysema (2); glioma (2); bronchiolitis (1); chromosome disorder (1); congenital heart disease (1); developmental delay (1); Infertility (1); learning disabilities (1); male infertility (1); myeloid leukemia (1); Paralysis (1); promyelocytic leukemia (1); tumor (1).